RNU2-65P (RNA, U2 small nuclear 65, pseudogene)
Gene: Small nuclear RNA gene on chromosome 15 (72,045,183 to 72,045,367, forward strand). Ensembl gene ENSG00000222094.
Homologues: Orthologues: chimpanzee U2 (61% identical), macaque U2 (56% identical), dog U2 (41% identical), rat LOC120097278 (36% identical), dog U2 (35% identical), pig U2 (33% identical), guinea pig U2 (31% identical), pig U2 (30% identical), dog U2 (29% identical). Paralogues in human: RNU2-14P (55% identical), RNU2-6P (55% identical), U2 (55% identical), RNU2-2 (54% identical), U2 (54% identical), RNU2-23P (52% identical), RNU2-8P (52% identical), RNU2-33P (52% identical), RNU2-3P (52% identical), RNU2-48P (52% identical), RNU2-56P (52% identical), RNU2-59P (52% identical), and 67 more.